LGALS9 (galectin 9)
Diseases named in the same sentence as LGALS9 in open-access papers (continued):
Sharing a sentence is not in itself a finding about the gene and the disease.
preeclampsia (9 papers, 2013 to 2023). Preeclampsia is a hypertensive disorder of pregnancy that is characterized by new-onset hypertension with proteinuria presenting after 20 weeks of gestation, and depending on mild or severe forms may initially present with severe headache, visual disturbances, and hyperreflexia. "Several studies have suggested a role for low galectin-9 expression and/or maternal serum levels in spontaneous miscarriages, recurrent pregnancy loss, and preeclampsia." (PMID 37189444, 2023). "The placental expressions of galectin-1 and galectin-13 were decreased in early pregnancy loss and preeclampsia, whereas the expressions of galectin-3 and galectin-9 were increased in preeclampsia." (PMID 33796532, 2021). "In a lipopolysaccharide-treated preeclampsia model, Tim-3 activation induced by galectin-9 could significantly upregulate IL-10 mRNA levels in dMφs." (PMID 36303229, 2022). "The possible involvement of the TIM-3/Galectin-9 pathway in the pathogenesis of unexplained miscarriages, recurrent spontaneous abortion (RSA), and preeclampsia (PE) has been studied by several groups, both in the periphery as well as at the MFI." (PMID 31057559, 2019). "The aim of our study was to investigate the expression and function of Galectin-9 and TIM-3 molecules by peripheral blood mononuclear cells and the possible role of Galectin-9/TIM-3 pathway in the immunoregulation of healthy pregnancy and early-onset preeclampsia." (PMID 23936526, 2013).
Stroke (9 papers, 2012 to 2025). Sudden impairment of blood flow to a part of the brain due to occlusion or rupture of an artery to the brain. "The aim of this study was to assess the expression patterns of serum galectin-1 (Gal-1), galectin-3 (Gal-3), galectin-9 (Gal-9), and galectin-3 binding protein (Gal-3BP) and their associations with stroke outcome in large artery atherosclerotic (LAA) stroke." (PMID 28112232, 2017). "Elevated blood galectin-9 levels were found in patients with stroke after 6 days of ischemic insult." (PMID 36873388, 2023). "In this study, we showed that protein expression of galectin-9 was increased as early as 5 hours after stroke, but Tim-3 levels were only increased 24 hours later." (PMID 22347410, 2012). "Western blot and immunostaining analysis showed that LRP inhibited protein expression of both galectin-9 and T-cell immunoglobulin domain and mucin domain 3 (Tim-3), which were increased after stroke." (PMID 22347410, 2012). "Results by Western blot suggest that the expression of galectin-9 was increased as early as 5 hours after stroke, and lasted at least to 24 hours." (PMID 22347410, 2012). "Tim-3 expression, which is downstream of galectin-9, was increased only at 24 hours after stroke, and this increase was inhibited by LRP." (PMID 22347410, 2012). "Nevertheless, galectin-9 was induced at 1 hour after stroke in the LRP group, which is earlier than that in the control group." (PMID 22347410, 2012). "Third, we further showed that the galectin-9/Tim-3 pathway is involved in neuronal injury after stroke, and LRP blocked its overexpression." (PMID 22347410, 2012). "For example, extracellular vesicle-mediated Lgals9 delivery improved the long-term functional recovery in photothrombotic stroke mice, suggesting Lgals9 could be a potential treatment target." (PMID 39633897, 2024). "In the rat model of ischemic stroke, galectin-9 expression is also increased, indicating that blocking galectin-9 function may have protective effects in stroke." (PMID 36873388, 2023). "In conclusion, LRP executes long-term protective effects against stroke and may block brain injury by inhibiting activities of the galectin-9/Tim-3 pathway, iNOS, and nitrotyrosine." (PMID 22347410, 2012). "The inhibitive effects of LRP on edema formation, BBB permeability, the galectin-9/Tim-3 pathway, and ROS activities, may contribute to its protective effects against stroke." (PMID 22347410, 2012). "Despite this, we found that LRP inhibited increases in both galectin-9 and Tim-3 expression at 24 hours post-stroke, suggesting that inhibition of the galectin-9/Tim-3 pathway may be a target for stroke therapy." (PMID 22347410, 2012). "We then investigated whether the novel galectin-9/Tim-3 cell signaling pathway, which causes TH1 cell death in the immune system, is involved in neuronal death after stroke." (PMID 22347410, 2012).
tuberculosis (9 papers, 2016 to 2024). A chronic, recurrent infection caused by the bacterium Mycobacterium tuberculosis. "Area under curve for Galectin-9 was >0.9 in HIV/tuberculosis co-infection and extrapulmonary tuberculosis." (PMID 32765475, 2020). "In this study, we investigated the role of a matricellular protein galectin-9 (Gal-9) in pleural effusion related to tuberculosis (TB)." (PMID 28657598, 2017). "Elevated matricellular proteins (MCPs), including osteopontin (OPN) and galectin-9 (Gal-9), were observed in the plasma of patients with Manila-type tuberculosis (TB) previously." (PMID 28025511, 2016). "Galectin-9 (Gal-9) and osteopontin (OPN) play immunomodulatory roles in tuberculosis and HIV infections." (PMID 32765475, 2020).
type 2 diabetes (9 papers, 2013 to 2025). "For example, the elevation of Galectin 9 (Gal-9) has been linked to inflammatory processes in both type 1 and type 2 diabetes." (PMID 37298672, 2023). "Similar to cystatin C, plasma galectin-9 has also been shown to be associated with aging-related comorbidities such as type 2 diabetes, atherosclerotic stroke, and coronary artery disease in various studies." (PMID 37569647, 2023). "In type 2 diabetes, increased serum galectin-9 correlates with declining GFR, while recombinant galectin-9 therapy in mouse models mitigates glomerular hypertrophy, albumin excretion, and TGF-β expression." (PMID 40904455, 2025).
Acute Hepatitis C (8 papers, 2010 to 2025). "Serum galectin-9 was elevated in hepatitis C infection and it was released from Kupffer cells in the liver." (PMID 23339460, 2013).
asthma (8 papers, 2011 to 2025). "Galectin-9 has demonstrated efficacy in a Dermatophagoides farinae allergen-induced asthma model by suppressing the expression of IL5, IL13, CCL11, CCL17, reducing eosinophilia, and pulmonary hyperresponsiveness." (PMID 41516283, 2025). "Among them, galectin-3 (Gal-3), galectin-9 (Gal-9), and galectin-10 (Gal-10) are the most extensively studied in human and animal asthma models." (PMID 38785528, 2024). "Interestingly, genes previously associated with asthma, such as CCL5 (RANTES), CXCL10 (IP10), LGALS9, CX3CL1, C5AR1, and CDHR3 fall into these three different groups." (PMID 25706956, 2015). "Interestingly, the changes in expression of lectin galactoside-binding soluble 9 (LGALS9), chemokine (C-X3-C motif) ligand 1 (CX3CL1) and complement component 5a receptor 1 (C5AR1) have been previously reported to be associated with asthma." (PMID 25706956, 2015). "They include RBM42, STX5, and TRIM41 in asthma, CYP27A1, GM2A, LGALS9, SPI1, and NLRC4 in COPD, as well as ATF3, PPP1R15A, ZFP36, SOCS3, NAMPT, and GADD45B in IPF." (PMID 31952466, 2020). "Galectin-9 binds to TIM-3, which is expressed on Th1 cells and is important for protective immunity against microbes and intravenous administration of Galectin-9 suppresses AHR and airway inflammation in a mouse model of asthma." (PMID 21867534, 2011). "These genes included RBM42, STX5, and TRIM41 in asthma, CYP27A1, GM2A, LGALS9, SPI1, and NLRC4 in COPD, ATF3, PPP1R15A, ZFP36, SOCS3, NAMPT, and GADD45B in IPF, LRRC48 and CETN2 in asthma-COPD, COL15A1, GIMAP6, and JAM2 in asthma-IPF and LMO7, TSPAN13, LAMA3, and ANXA3 in COPD-IPF." (PMID 31952466, 2020).
colitis (8 papers, 2020 to 2026). Inflammation of the colon. "Galectin 4 (Gal-4) is associated with an increase in the pro-inflammatory interleukin 6 (IL-6) during colitis, while Galectin 9 (Gal-9) is associated with an increase in the anti-inflammatory role during EAE by favoring the apoptosis of Th1 cells." (PMID 40650248, 2025). "This study investigated the effect of endogenous Galectin-9 (Gal-9), as well as the combined effects with Galectin-3 (Gal-3), in modulating disease progression in murine models of colitis, using global knockout (KO) models for Gal-3, Gal-9, and Gal-3/Gal-9." (PMID 39951917, 2025). "Here, the authors show that galectin-9 has specific lysosomal roles in autophagy and contributes to cell degeneration and apoptosis in colitis and pancreatitis in mice." (PMID 32855403, 2020). "On the other hand, findings from HAVCR2 polymorphisms and modulation experiments in autoimmune diseases and IBD, using TIM-3 with blocking antibodies or activation by its ligand galectin-9, rather indicate a predominant inhibitory role, particularly in colitis." (PMID 41483156, 2026). "Vice versa, the TIM-3 ligand Galectin-9 has been recently demonstrated to reduce 2,4,6-trinitrobenzene sulfonic acid (TNBS)-induced colitis in mice." (PMID 38363399, 2024). "Increased LGALS9 expression in humans is positively correlated with augmentation of T-cell markers and proinflammatory cytokines such as IL1B and IL6 in the affected intestines, which also has positive correlation to the severity of colitis." (PMID 35794311, 2022).
cytomegalovirus infection (8 papers, 2015 to 2023). A herpesvirus infection caused by Cytomegalovirus. "To validate the transcriptomic data, we performed quantitative real-time PCR (RT-qPCR) and immunoblot to analyze the effect of ectopically expressed UL23 on the expression of APOL1, CMPK2, and LGALS9 upon IFN-γ stimulation or HCMV infection." (PMID 37112994, 2023). "Cytomegalovirus infection also induces higher production of IFN-γ from hepatic NK cells in galectin-9 knockout mice than in control mice." (PMID 28991189, 2017). "Interestingly, the mechanisms involved in cytomegalovirus infection are reminiscent of the influenza A virus infection, such that galectin-9 knockout mice have a stronger virus-specific CD8+ T cell response that develops during the acute phase than do control mice." (PMID 28991189, 2017). "As expected, UL23 significantly restricted IFN-γ-induced gene expressions of APOL1, CMPK2, and LGALS9; UL23 also significantly reduced their expression during HCMV infection." (PMID 37112994, 2023). "Interestingly, galectin-9 knockout mice demonstrate increased IFN-γ production by NK cells and enhanced NK cell degranulation in response to cytomegalovirus infection, suggesting that whilst galectin-3 has a negative impact on NK cell function in the TME, the reverse may be the case for galectin-9." (PMID 33187209, 2020).
Hodgkins lymphoma (8 papers, 2006 to 2025). A heterogeneous group of malignant lymphoid neoplasms of B-cell origin characterized histologically by the presence of Hodgkin and Reed-Sternberg (HRS) cells in the vast majority of cases. "One of the first descriptions of Galectin-9 was in 1997, after which it was cloned and identified as a tumor antigen in Hodgkin’s lymphoma." (PMID 29361803, 2018). "Galectin 9, a β-galactoside-binding protein, was originally characterized in Hodgkin's lymphoma cells and has various immunomodulatory properties." (PMID 17156439, 2006). "Galectin-9 was initially functionally described in Hodgkin-Lymphoma in 1997." (PMID 39000016, 2024). "Similar hypotheses might also be relevant to Hodgkin lymphomas where galectin 9 expression has been initially reported and which is associated to EBV in about 50% of the cases with consistent and intense expression of LMP1." (PMID 17156439, 2006). "Since both LMP1 and galectin 9 are known to have effects on immune response mechanisms, these observations are likely to improve our understanding of host-tumor relationships in NPC and possibly in Hodgkin's disease." (PMID 17156439, 2006).
lung fibrosis (8 papers, 2020 to 2025). "Given that galectin-9 promotes differentiation into M2-type macrophages, these findings suggest that galectin-9 can stimulate monocyte/macrophage activity and contribute to lung fibrosis especially in anti-MDA5 antibody-positive DM." (PMID 40181992, 2025). "We found that the levels of fibrotic markers such as αSMA, CTGF, and collagen were significantly higher in the bleomycin-induced lung fibrosis model than controls, suggesting a suitable model for assessing the role of galectin-9 in the lung fibrosis accompanying SSc." (PMID 31937306, 2020). "Lung fibrosis was induced using bleomycin in galectin-9 wild-type and knockout mice." (PMID 31937306, 2020). "Therefore, we next investigated the effect of galectin-9 on pulmonary fibrosis induced by bleomycin in mice." (PMID 31937306, 2020). "However, the role of galectin-9 in the pulmonary fibrosis of SSc remains unknown." (PMID 31937306, 2020).
multiple sclerosis (8 papers, 2014 to 2025). A progressive autoimmune disorder affecting the central nervous system resulting in demyelination. "Another biomarker extensively studied in multiple sclerosis, precisely for the differentiation between relapsing–remitting and secondary progressive phenotypes, is represented by galectin-9." (PMID 40362691, 2025). "In inactive multiple sclerosis lesions, galectin-9 is localized in the cytoplasmic region, but in active lesions it is present in both the cytoplasm and the nucleus." (PMID 36008956, 2022). "The interaction between murine TIM3 and its ligand galectin-9 (Gal9) inhibits T cell proliferation and cytokine secretion in vitro and in vivo in murine models of multiple sclerosis." (PMID 26967901, 2016). "Galectin-9 was proven to play a crucial role in immune regulation (via T cell immunoglobulin and mucin-domain protein 3), with later evidence of elevated levels in the CSF of patients with multiple sclerosis and NMOSD." (PMID 40362691, 2025). "Patients with multiple sclerosis (MS) have higher levels of galectin-9." (PMID 36008956, 2022). "Galectin-9 (Gal-9) has been shown to significantly reduce pathology of experimental autoimmune encephalomyelitis (EAE), a mouse model of multiple sclerosis, whereas Gal-1 prevents ocular pathology in EAU as well as EAE." (PMID 26126176, 2015).
non-small cell lung carcinoma (8 papers, 2018 to 2025). A group of at least three distinct histological types of lung cancer, including non-small cell squamous cell carcinoma, adenocarcinoma, and large cell carcinoma. "Plasma exosomal Tim-3 and Galectin-9 protein molecules exhibited significantly higher levels in patients with non-small cell lung cancer (NSCLC) than in healthy controls." (PMID 38983854, 2024).
acute lymphoblastic leukemia (7 papers, 2010 to 2025). Leukemia with an acute onset, characterized by the presence of lymphoblasts in the bone marrow and the peripheral blood. "Here we show that the adipocyte secretome upregulates the surface expression of Galectin-9 (GAL-9) on human B-acute lymphoblastic leukemia cells (B-ALL) which promotes chemoresistance." (PMID 35241678, 2022). "Prior work has demonstrated that caspase-1 is involved in galectin-9-mediated apoptosis of the MOLT-4 lymphoblastic leukemia cell line; we found that caspase 8 mediated antigen induced cell death of HCV-specific CTLs." (PMID 20209097, 2010). "We aimed to evaluate the mRNA expression of VISTA, Galectin-9, and TIM-3 on CD8+ T-cells and leukemic cells in B-cell acute lymphoblastic leukemia (B-ALL)." (PMID 37970435, 2023).
cervical squamous cell carcinoma (7 papers, 2016 to 2025). A squamous cell carcinoma arising from the cervical epithelium. "In cervical squamous cell carcinoma, DCs express immunosuppressive molecules such as indoleamine 2,3-dioxygenase 1 (IDO1) and galectin-9 (LGALS9), while exhibiting low PD-L1 expression, revealing spatially heterogeneous mechanisms of immune suppression." (PMID 41050070, 2025). "In our study, higher mRNA levels of the LGALS9 gene were detected in HaCaT nontumoural cells, whereas SiHa and HeLa CC cells, which are derived from cervical squamous cell carcinoma and adenocarcinoma, respectively, exhibited low expression of the gene." (PMID 32902187, 2020).
cholangiocarcinoma (7 papers, 2018 to 2025). A carcinoma that arises from the intrahepatic biliary tree (intrahepatic cholangiocarcinoma) or from the junction, or adjacent to the junction, of the right and left hepatic ducts (hilar cholangiocarcinoma). "In cholangiocarcinoma, Galectin-9 induces cell apoptosis and inhibits the proliferation of TFK-1 and HuH-28 cholangiocarcinoma cell lines, with an increase in CCK-18 and cytochrome c." (PMID 36358792, 2022).
chronic myelogenous leukemia (7 papers, 2017 to 2022). "On the other hand, administration of galectin-9 increases the sensitivity of chronic myeloid leukemia to the BCR-ABL tyrosine kinase drug imatinib." (PMID 34572756, 2021). "Tim-3 and galectin-9 were present in all the studied cancer cells, except for the chronic myeloid leukemia (CML) cell line, K562, which expressed Tim-3 but only traces of galectin-9, in agreement with previously reported observations." (PMID 31354733, 2019). "Importantly, in healthy human cells (keratinocytes) expressing barely detectable amounts of galectin-9, TGF-β cannot induce galectin-9 expression, while if cancer cells (for example K562 chronic myeloid leukaemia cells) express only traces of galectin-9, TGF-β can induce expression of this protein." (PMID 33295886, 2020). "To find out whether such a phenomenon (the absence of induction of galectin-9 expression by TGF-β) applies also to cancer cells we used K562 chronic myeloid leukaemia cells which express only traces of galectin-9 protein compared to for example THP-1 or other AML cells." (PMID 33295886, 2020). "Finally, in order to assess whether soluble VISTA suppresses the cytotoxic activity of T cells we used K562 chronic myeloid leukemia cells, which express traces of galectin-9 and VISTA but do not release detectable amounts of these proteins." (PMID 35634346, 2022).
coronary artery disease (7 papers, 2015 to 2025). "Increased serum galectin-9 levels were also observed in patients with stable coronary artery disease, suggesting an important role of galectin-9 in cardiovascular pathology." (PMID 36873388, 2023).
esophageal squamous cell carcinoma (7 papers, 2019 to 2025). Esophageal squamous cell carcinoma (ESCC) is a type of esophageal carcinoma (EC) that can affect any part of the esophagus, but is usually located in the upper or middle third. "Nevertheless, in a follow-up study by the same group, the growth inhibitory and pro-apoptotic effects of galectin-9 were confirmed in esophageal squamous cell carcinomas using different in vitro and in vivo models." (PMID 36497271, 2022).